DSC3 (desmocollin 3)
Description:
A component of desmosome cell-cell junctions which are required for positive regulation of cellular adhesion (By similarity). Required for cell-cell adhesion in the epidermis, as a result required for the maintenance of the dermal cohesion and the dermal barrier function. Required for cell-cell adhesion of epithelial cell layers surrounding the telogen hair club, as a result plays an important role in telogen hair shaft anchorage (By similarity). Essential for successful completion of embryo compaction and embryo development (By similarity).
Synonyms: CDHF3; DSC4; DSC; DSC1; DSC2; HT-CP
Tractability: Antibody: UniProt places it where antibodies can reach, with high confidence; its Gene Ontology location is reachable by antibodies, with high confidence; UniProt predicts a signal peptide or a membrane-spanning region; the Human Protein Atlas places it where antibodies can reach. PROTAC: ubiquitination databases record sites on it.
Gene: Protein-coding gene on chromosome 18 (30,989,365 to 31,042,815, reverse strand). Ensembl gene ENSG00000134762.
Subcellular location: Cell membrane; Cell junction, desmosome; Cytoplasm
Subcellular location (Human Protein Atlas): Cell Junctions; Plasma membrane
Pathways (Reactome):
Developmental Biology: Formation of the cornified envelope; Keratinization
Gene Ontology:
Molecular function: protein binding; calcium ion binding
Biological process: cell-cell adhesion; cell adhesion; homophilic cell-cell adhesion
Cellular component: cell junction; cell-cell junction; plasma membrane; cornified envelope; cytoplasm; desmosome; membrane; extracellular region
Genetic constraint (gnomAD): Loss-of-function variants: 86 observed, 80.98 expected, observed/expected ratio (o/e) 1.06, 90% interval 0.89 to 1.27. The upper end of that interval is the gene's LOEUF score, 1.27, which puts it in group 5 of 6, group 1 being the genes least tolerant of losing a copy. Missense variants: 1,162 observed, 1,096.4 expected, observed/expected ratio (o/e) 1.06, 90% interval 1.01 to 1.11. Synonymous variants: 425 observed, 388.81 expected, observed/expected ratio (o/e) 1.09, 90% interval 1.01 to 1.18.
Homologues: Orthologues: chimpanzee DSC3 (99% identical), macaque DSC3 (96% identical), rabbit DSC3 (85% identical), dog DSC3 (85% identical), pig DSC3 (82% identical), mouse Dsc3 (80% identical), rat Dsc3 (79% identical), tropical clawed frog dsc3 (36% identical), zebrafish dsc2l (36% identical). Paralogues in human: DSC2 (67% identical), DSC1 (51% identical), DSG4 (28% identical), DSG3 (27% identical), DSG2 (26% identical), DSG1 (23% identical).
Diseases named in the same sentence as DSC3 in open-access papers:
DSC3 is named in the same sentence as 59 diseases in open-access papers, as found by Europe PMC text mining. Sharing a sentence is not in itself a finding about the gene and the disease. The quoted sentences say what the papers report.
melanoma (12 papers, 2011 to 2025). A malignant, usually aggressive tumor composed of atypical, neoplastic melanocytes. "In melanoma, elevated levels of the cadherin desmocollin 3 (DSC3) has been associated with increased metastatic risk, but in colon and lung cancer, it has been associated with a better prognosis." (PMID 34527572, 2021). "Additionally, elevated level of DSC3 was reported to increase metastatic risk in melanoma, whereas DSC3 was associated with better prognosis in lung and colon cancer." (PMID 29348685, 2018). "However, in melanoma, elevated DSC3 was linked to increased metastatic risk." (PMID 29348685, 2018). "Immune infiltration analysis revealed a significant correlation between the expression levels of DSC2, DSC3, and the infiltration of various immune cells, highlighting the intricate relationship between the tumor microenvironment and melanoma progression." (PMID 38660305, 2024). "For example, DSC3 was upregulated in primary melanoma than in metastatic melanoma, its high expression level was correlated with adverse prognosis." (PMID 33392203, 2020). "This relationship between DSC3 and survival is also described in melanoma and ovarian cancer." (PMID 40422563, 2025). "Then, we identified 9 LR pairs (“BMP6- > HJV” 、"CCL8- > ACKR4” 、"DLL3- > NOTCH3"、"DSC3- > DSG3"、"GHRH- > GHRHR” 、"LRRC4B- > PTPRF"、"SEMA4D- > PLXNB1"、"SFRP1- > FZD6"、"UCN- > CRHR1′′) as key LR pairs in melanoma prognosis through Lasso Cox regression and Multiple Stepwise Regression." (PMID 36777724, 2023). "Currently available literature indicates DSC3 expression by squamous NSCLC, ovarian cancer, cervical cancer, melanoma, colorectal cancer, meningioma, esophageal squamous cell carcinoma, sarcoma, and pediatric acute lymphoblastic leukemia." (PMID 39534596, 2024). "Our analysis, grounded in WGCNA and PPI networks, identified six genes (DSC2, DSC3, DSG1, KRT6B, PKP1, PKP3) with pivotal roles in melanoma’s oxidative stress response and immune infiltration." (PMID 38660305, 2024). "As the expression levels of DSC2, DSC3, DSG1, KRT6B, PKP1, and PKP3 increased, the overall survival time of trunk subtype melanoma patients significantly decreased." (PMID 38660305, 2024). "DSC3 is also expressed in many types of cancers, including squamous NSCLC, head and neck cancer, melanoma, esophageal, colorectal, chondrosarcoma, pediatric acute lymphoblastic leukemia, and ovarian, among others." (PMID 39534596, 2024). "The results showed that the expression of DSC3, DLL3, BMP6, SEMA4D, and GHRH are increased (p < 0.05) in melanoma, while the expression of LRRC4B, SFRP1, DCN, and CCL-8 decreased in melanoma (p < 0.05)." (PMID 36777724, 2023). "DSC-3 and SFRP1 are biomarkers with suppressive properties, affecting the metastasis and transfection of melanoma." (PMID 36777724, 2023). "In contrast, expression of other desmosomal cadherins (DSG1, DSG3, DSC1, DSC2, DSC3) was negligible, revealing that DSG2 is unique within this gene family for its expression in a large proportion of melanoma cell lines." (PMID 27340778, 2016). "Some of these genes had already been described in earlier studies as being down-regulated during melanoma progression: COL17A1, DSC3, KLK7, SLPI and KLK8, or over-expressed, e.g. CCL20, THBS1 and THBS4." (PMID 22032772, 2011). "The results indicate that in trunk subtype melanomas, the protein expression levels of DSC2, DSC3, DSG1, KRT6B, PKP1, and PKP3 are significantly higher than those in adjacent normal samples, suggesting the crucial roles of these central genes in SKCM progression." (PMID 38660305, 2024). "One explanation of this negative correlation between DSC3 and TIL is the barrier function of DSC3, an adhesion molecule, toward immune infiltration as described in melanoma and ovarian cancer." (PMID 40422563, 2025).
breast carcinoma (10 papers, 2005 to 2025). "Cancer development and progression are associated with either loss of DSC3 expression, as seen in prostate or breast cancer, or overexpression of DSC3 including its cytoplasmic expression as seen with squamous non-small-cell lung cancer and colorectal cancer." (PMID 40422563, 2025). "Desmocollin 3 was found to be downregulated in breast and oral cancer, and gene silencing in breast cancer was caused by promoter hypermethylation." (PMID 21364582, 2011). "The finding that the DSC3 gene is frequently silenced by epigenetic mechanisms in breast cancer opens new avenues to understanding the underlying causes of malignant progression in breast cancer and helps to identify new targets for therapeutic intervention." (PMID 16168112, 2005). "DSC3 gene silencing is linked to aberrant cytosine methylation in 41% of the primary breast carcinomas tested." (PMID 16168112, 2005). "The loss of DSC3 expression in primary breast carcinomas and tumor cell lines has been previously reported." (PMID 16168112, 2005). "DSC3 expression is down-regulated in breast cancer cell lines and primary breast tumors; however, the loss of DSC3 is not due to gene deletion or gross rearrangement of the gene." (PMID 16168112, 2005). "Recent studies have observed loss of DSC3 in several cancer types, such as lymph node metastases of oral squamous cell carcinoma, breast cancer and colorectal cancer, where the decreased levels associated with cancer progression were regulated by epigenetic modification." (PMID 24664224, 2014). "In addition, analysis of breast cancer cell lines showed that DSC3 is silenced in association with cytosine hypermethylation and histone deacetylation." (PMID 16168112, 2005). "DSC3 is a component of desmosomes, and its expression is down-regulated in breast cancer cell lines and primary breast tumors." (PMID 36293530, 2022). "Another study showed a downregulation of the desmosomal cadherin desmocollin 3 in human breast carcinoma cell lines using cDNA microarray analysis." (PMID 36293530, 2022). "In breast cancer, the metastasis suppressor genes desmocollin 3 (DSC3) and MASPIN, for instance, were reported to be frequently silenced by an epigenetic mechanism." (PMID 26441991, 2015). "A couple of exceptions are studies in which the desmosomal protein Dsc3 was found to be downregulated during human breast cancer development, and in which Dp expression was observed to be inversely correlated with human breast tumor growth and progression." (PMID 22515648, 2012). "As such, the identification of DSC3 as a gene that is commonly downregulated in breast cancer necessitates the need for further examination of its role in breast tumor progression." (PMID 16168112, 2005). "DSC3 expression was downregulated in 23 of 32 (72%) breast cancer specimens comprising: 22 invasive ductal carcinomas, 7 invasive lobular breast carcinomas, 2 invasive ductal carcinomas that metastasized to the lymph node, and a mucoid ductal carcinoma." (PMID 16168112, 2005). "SERPINB5 has been indicated to inhibit tumor progression, DSC3 downregulation has been linked with several cancer types and GABRP over-expression has been linked with poor prognosis, metastatic cancer, basal-like breast cancer." (PMID 39580456, 2024). "The desmocollin 3 gene DSC3 is a member of the cadherin superfamily of calcium-dependent cell adhesion molecules, an important component of desmosomes and its expression is down-regulated in breast cancer cell lines and primary breast tumors." (PMID 36293530, 2022).
breast carcinoma (continued). "By contrast, DSC3 was downregulated in breast cancer due to promoter hypermethylation." (PMID 21364582, 2011). "Down-regulation of DSC3 in breast cancer was first reported by Klus." (PMID 16168112, 2005). "So far, no genetic changes including mutation, deletion, and gene rearrangement of DSC3 have been found in cancer, and except for the detailed description of methylation patterns in breast cancer, no methylation analysis of DSC3 in any other tumour entity has been reported." (PMID 21364582, 2011). "Meanwhile, epigenetic silencing caused by methylation was previously observed for at least five ASE genes identified in our study, including DSC3, FGFR2 and MGMT in breast cancer and/or in other cancer types." (PMID 21108794, 2010). "Furthermore, using in vitro models we show that the epigenetic silencing of DSC3 is due in part to cytosine methylation of its promoter region and to concomitant changes in chromatin structure that lead to it forming a closed, inaccessible conformation in the breast cancer cell lines." (PMID 16168112, 2005). "Some genes associated with cell adhesion were analyzed from this radiation- and estrogen-induced experimental breast cancer model, including E-cadherin gene CDH1, DSC3, GJA1, the Integrin alpha 6 gene ITGA6, the Integrin beta 6 gene ITGB6, the Keratin genes KRT14, KRT16, KRT17, KRT6B, and LAMB3." (PMID 36293530, 2022).
pemphigus (10 papers, 2019 to 2023). Pemphigus is a group of rare autoimmune diseases that cause blistering of the skin and mucous membranes (mouth, nose, throat, eyes, and genitals).This conditioncan occur at any age, but often strikes people in middle or older age. "From a clinical point of view, although a few cases of mucosal dominant‐type PV with exclusive anti‐Dsc3 autoantibodies have been reported, most of the anti‐Dsc3 autoantibody positive cases belong to atypical variants of pemphigus." (PMID 36578135, 2023). "Pemphigus is a life-threatening bullous autoimmune disease in which autoantibodies against Dsg1, Dsg3, Dsc3 as well as other antigens cause flaccid blistering in the epidermis and in mucous membranes of the oral cavity and elsewhere." (PMID 36624106, 2023). "For example, whilst the pathophysiology of anti-Dsg pemphigus is dominated by the activation of p38MAPK and is associated with desmosome disassembly, anti-Dsc3 and anti-SPCA1 AuAbs activate SRC proto-oncogene, cytochrome c release, and caspase-9 activity in patients with anti-Dsg-negative PV." (PMID 36979046, 2023). "Dsc3-reactive IgG antibodies purified from sera of pemphigus patients could induce the loss of adhesion of epidermal keratinocytes in a dispase-based keratinocyte dissociation assay." (PMID 37189450, 2023). "In addition, anti-Dsc3 antibodies in sera of pemphigus patients were proved to mainly recognize the extracellular 2 domain of Dsc3, and antibodies against the extracellular 2 domain of Dsc3 have pathogenic roles in keratinocyte dissociation." (PMID 37189450, 2023). "It is now possible to recapitulate the active models of PV, PF, Mucocutaneous Pemphigus and the Atypical anti-DSC3 pemphigus." (PMID 37237515, 2023). "Although these studies proved the possible involvement of anti-Dsc3 antibodies in the pathogenesis of pemphigus, more deep studies are necessary to elucidate it clearly." (PMID 37189450, 2023). "On the other hand, an active disease model of pemphigus expressing anti‐Dsc3 autoantibodies or anti‐Dsc3 and anti‐Dsg3 autoantibodies were developed the pathogenic activity of anti‐Dsc3 autoantibodies." (PMID 36578135, 2023). "On the contrary, the other pemphigus models (DSC3/DSG3 and DSG3) appear to be only partially responsive to m-PSL." (PMID 31275323, 2019). "In order to verify the pathogenic activity of anti-Desmocollin 3 (DSC3) antibodies, we developed an active disease model of pemphigus expressing anti-DSC3 autoantibodies or anti-DSC3 and anti-DSG3 antibodies." (PMID 31275323, 2019). "Dsc3 active model was supported the concept that antigens other than Dsgs may be responsible for different phenotypes in pemphigus." (PMID 36578135, 2023). "Previous studies have shown that IgG and IgA antibodies in patients with IgG/IgA pemphigus could target Dsg1, Dsg3, and/or desmocollin 1 (Dsc1)–Dsc3 to a different extent, which may account for the mixed clinical presentations of the disease." (PMID 35625932, 2022). "All in all, the DSC3 phenotype may resemble that observed in so-called atypical pemphigus in humans where clinical presentation is always milder than in PV or PF." (PMID 31275323, 2019). "On the other hand, this might also suggest that the role of DSC3 alone can only account for a milder form of pemphigus." (PMID 31275323, 2019). "In particular, we have shown the contribution of DSC3 in the genesis of pemphigus." (PMID 31275323, 2019). "More recently, autoantibodies against Dsc1 and Dsc3, mitochondrial proteins, human leukocyte antigens, molecules, thyroid peroxidase (TPO), a Ca2+/Mn2+-ATPase encoded by ATP2C1 (hSPCA1), and several muscarinic and nicotinic AChRs have been identified as novel targets for pemphigus autoimmunity." (PMID 36979046, 2023). "DSG3 and DSC3/DSG3 pemphigus models only partially responded to therapy, while m-PSL was very efficacious in improving the DSC3 model, as shown by PV Score and DSC3 antibody titer." (PMID 31275323, 2019).
pemphigus (continued). "Altogether, the two pemphigus models reacting against DSG3 have a higher PV score, as compared to the DSC3 mice." (PMID 31275323, 2019). "To better understand the pathogenic role of non-DSG autoantibodies, here we report the first DSC3 active pemphigus mouse model." (PMID 31275323, 2019). "Moreover, ADAM10 inhibition was shown to be protective in a murine pemphigus model when antibodies against Dsg1 and Dsg3, but not Dsc3, were present in the patient sera." (PMID 35844545, 2022). "In conclusion, we have developed an adult DSC3 pemphigus mouse model that differs from the DSG3 model and supports the concept that antigens other than desmogleins may be responsible for different phenotypes in human pemphigus." (PMID 31275323, 2019). "The presence of anti‐Dsc3 autoantibodies was sufficient to determine the appearance of a pathological phenotype relatable to pemphigus, but with features not completely superimposable to those observed in the Dsg3 active model, suggesting that the Dsc3 active model might mimic atypical pemphigus." (PMID 36578135, 2023).
colorectal cancer (8 papers, 2006 to 2025). A primary or metastatic malignant neoplasm that affects the colon or rectum. "Promoter DNA hypermethylation of DSC3, which suppressed host gene expression, has been associated with poor OS of colorectal cancer and recurrence of prostate cancer." (PMID 34034702, 2021). "Switching from desmocollin-2 to desmocillin-3 has been noted in colorectal cancer development and the methylation of the DSC3 promoter is a prognostic marker of colorectal cancer." (PMID 25929336, 2015). "In this report, we show for the first time that Dsc2 protein expression is reduced in colorectal cancer, and that this is accompanied by de novo expression of Dsc1 and Dsc3." (PMID 17088906, 2006). "Moreover, DSC3 was downregulated in colorectal cancer cells, and its methylation status was shown to be an effective prognostic marker." (PMID 38652547, 2024). "However, the role of DSC3 in colorectal cancer (CRC) has not yet been established." (PMID 21364582, 2011).